IL6 (interleukin 6)
Diseases named in the same sentence as IL6 in open-access papers (continued):
Sharing a sentence is not in itself a finding about the gene and the disease.
cancer (continued). "Other cytokines such as IL-22, IL-11, and IL-6 have been implicated in enhancing stem cell phenotypes in cancer, and because these cells are less proliferative and less metabolically active, they thus become less sensitive to many forms of chemo- and radiotherapy." (PMID 39766152, 2024). "Studies have shown significant reductions in inflammatory markers such as C-reactive protein (CRP), tumor necrosis factor-alpha (TNF-α), and interleukin-6 (IL-6) among individuals adhering to the MD, suggesting its pivotal role in mitigating chronic inflammation-associated with cancer development." (PMID 38773621, 2024). "This supports the hypothesis of a shared inflammatory etiology between PH and various cancer types, particularly through genes such as IL6 and IL1B that are strongly associated with inflammation and immune responses." (PMID 39635438, 2024). "The correlation analysis revealed that the six signature genes were positively correlated with IL-6 and IL-20 indicating the dysregulation of these genes may hamper the regulation of IL-6 and IL-20 and may cause cancer progression." (PMID 38172584, 2024). "IL-6 is also implicated in acquiring malignant features in various cancers, including OSCC." (PMID 38510850, 2024). "Consistently, GSEA-Hallmark analysis reveals significantly elevated enrichment scores for immune-associated and cancer-related signaling pathways, including epithelial-mesenchymal transition, Interferon-gamma response, inflammatory response, and IL6/JAK/STAT3 pathways." (PMID 38763954, 2024). "Of note, increased IL-6 and IL-8 levels are associated with poor response of cancer cells to GSIs." (PMID 38233409, 2024). "Indeed, elevated levels of circulating IL-6 are associated with cancer progression and cachexia in patients and animal models." (PMID 38824130, 2024). "In cancer pain, key ILs implicated include IL-1, IL-6, IL-10, IL-17, IL-18, and IL-33." (PMID 38940936, 2024). "Notably, IL-6 expression is associated with a poor prognosis in various types of cancer, including sporadic and colitis-associated cancers." (PMID 38671854, 2024). "Recently, it was shown that IL-6-induced autophagy can also contribute to cancer cachexia, a condition characterized by severe loss of body weight and increased muscle wasting and is associated with an increased risk of cancer treatment failure and poor overall survival." (PMID 38660307, 2024). "Elevated levels of IL-6 have also been implicated in cancer cachexia." (PMID 38674936, 2024). "Additionally, interleukin-6 (IL-6), a pro-inflammatory protein associated with cancer progression, significantly impacts cholesterol metabolism through various pathways." (PMID 39767804, 2024). "The IL-6/STAT3 signaling pathway is also essential in inflammation-associated cancers." (PMID 39061221, 2024). "A recent study revealed that IL-6 causes EMT in carcinoma cells." (PMID 38904007, 2024). "The authors suggested that IL-6 may be more valuable in the early stages of cancer cachexia with increased acute phase proteins causing tissue wasting." (PMID 37906352, 2023). "In addition, the IL6-JAK-STAT3 pathway is abnormally overactivated in numerous cancer types, which is often associated with poor outcomes." (PMID 37927783, 2023). "Furthermore, cancer cells can release TGF-β or IL-6 in the TME to activate cancer-associated fibroblasts (CAFs), that in turn can contribute to the suppression of NK cells cytotoxicity and cytokine production." (PMID 38077389, 2023). "Interestingly, blocking IL-6 or inhibiting its associated signaling has been proposed to be a potential therapeutic strategy for the treatment of cancers with IL-6-dominated signaling." (PMID 36909942, 2023). "Additionally, IL-6 and G-CSF have been widely implicated in cancer invasiveness and recent studies have also shown a role of trans-IL-6 activating JAK/STAT signaling in dormancy awakening." (PMID 37699010, 2023). "IL-6 is a pleiotropic cytokine that is implicated in various cancers." (PMID 37941042, 2023).
cancer (continued). "Moreover, an association between IL-6 serum levels and unfavorable prognosis has also been observed in many cancers other than PCa." (PMID 37108754, 2023). "Dietary interventions may help to decrease chronic inflammation by decreasing inflammatory biomarkers such as CRP, IL6 that are associated with fatigue in cancer patients." (PMID 36839371, 2023). "In addition to STAT3, the involvement of transcription factors such as NF-κB and C/EBPβ in EMT has also been described in human cancers, leading us to explore the possible association between IL-6 and NF-κB or C/EBPβ in HCT116 cells." (PMID 37047623, 2023). "CRP is produced by the hepatocytes in response to the release of the inflammatory cytokines, e.g., interleukin 6 (IL-6), and high concentration (>10 μg/mL) has been associated with advanced cancer stages, metastasis, and poor prognosis in different cancer types including NSCLC." (PMID 38001689, 2023). "Interestingly, Netrin‐1 upregulation was also reported in CAF to be associated with increased cancer cell stemness, through IL6 modulation." (PMID 36587397, 2023). "IL6 could be secreted from various cells in cancer tissues, including myeloid cells, cancer-associated fibroblasts, and cancer cells." (PMID 37454220, 2023). "Moreover, recent evidence showed that IL-6 secreted from cancer-associated fibroblasts (CAFs) triggers epigenetic changes in cholangiocytes, stimulating a malignant transformation towards iCCA." (PMID 38275386, 2023). "IL-6 and TNFα have both been implicated in cancer cachexia, and efforts to block these cachexins may also improve responses to cancer-directed therapies." (PMID 37461742, 2023). "The cytokine most often implicated in STAT3-driven cancer pathogenesis is IL-6." (PMID 38022653, 2023). "Furthermore, this anti-inflammatory effect of SC-1 is mediated via inhibition of p38 MAPK phosphorylation and then NF-κB activation leading to the mRNA expression associated with pro-inflammatory cytokines, IL-6, in human cancer cells." (PMID 37511415, 2023). "Il-6 and Il-8 are considered oncogenic cytokines because they are associated with epithelial-mesenchymal transition, disrupting intercellular interactions, hindering macrophage function, and promoting cancer cell invasion." (PMID 38258051, 2023). "In addition, IL-6 production by ageing cells is associated with age-dependent pathologies and cancer." (PMID 37753372, 2023). "The IL-6 cytokine could be the main soluble mediator involved in the inflammation associated with cancer, modulated by H. junceus scorpion venom." (PMID 38137888, 2023). "The addition of DMAPT reduced circulating IL‐6 and prevented weight loss, suggesting it may be beneficial for cancer patients undergoing platinum therapy." (PMID 37533407, 2023). "Furthermore, cancer-associated adipocytes (CAA) can trigger increased expression of pro-inflammatory cytokines IL6 and IL8 in co-cultures with TNBC cells MDA-MB-231." (PMID 37445860, 2023). "As a result, from recent progress in cancer research, there is an emerging number of endogenous substances associated with inflammation and cancer to choose between, e.g., NF-κB, IL-6, IFN-γ, TNF-α, enzyme indoleamine-2,3-dioxygenase (IDO), and BRAF gene mutations." (PMID 37631245, 2023). "Also, when anti-IL-6-antibody drugs were implemented in non-small cell lung cancer patients, there were significant improvements in anemia, cancer-associated cachexia, and fatigue resistance." (PMID 37755304, 2023). "In addition, studies have revealed that cancer-associated fibroblasts secrete IL-6 into the NSCLC TME, resulting in chemoresistance and increased metastatic potential." (PMID 37120670, 2023). "In a recent study, cancer-associated fibroblasts were activated by the CM-derived exosomes to a greater degree than normal fibroblasts for the transcription of genes for proinflammatory cytokines and chemokines, mainly IL-6 or IL-8." (PMID 36831440, 2023).
cancer (continued). "Administration of L. reuteri suppressed keratinocyte chemoattractant (KC), Il22, Il6, Tnf, and IL1α gene expression in the colonic mucosa and reduced the amounts of proinflammatory, cancer-associated cytokines, keratinocyte chemoattractant, IL-22, and IL-6, in plasma." (PMID 36295796, 2022). "Specifically, IL-6 can promote pro-inflammatory signaling that is linked to cancer progression; it is highly expressed in many cancer types, including colorectal, breast, lung, and pancreatic cancer; correlates with poor survival, and aids in EMT-mediated cancer cell invasion." (PMID 35563790, 2022). "However, a recent observational study confirmed lack of association between the use of anti-TNF, anti-CD20, or anti-IL6 and malignancy compared to DMARDs naïve patients." (PMID 36104053, 2022). "Moreover, recent studies reported that the IL-6/JAK/STAT3 signaling pathway is associated with glycolysis metabolism of cancer cells." (PMID 35090515, 2022). "Therefore, since IL-6 plays a central role in the invasion-metastasis cascade, which is the leading cause of cancer-related deaths worldwide, it is an absolutely obligatory avenue for novel pharmacological interventions." (PMID 36429126, 2022). "Second, humoral biomarkers should also be considered, since elevated levels of pre-existing antibodies or inflammatory cytokines act as triggers for the development of irAEs; IL-6, IL-17, and sCD163 are significantly associated with irAEs in cancer patients treated with ICIs." (PMID 35774996, 2022). "Associated with inflammation, IL-6 is involved in the progression of cancer." (PMID 36591515, 2022). "In addition, cancer-associated fibroblasts (CAFs) can induce PD-L1 expression on neutrophils to impair T-cell function by IL-6 - Stat3 signaling pathway." (PMID 36016960, 2022). "It has been reported that interleukin-6 is produced by cancer-associated mesenchymal stem cells." (PMID 35071777, 2022). "IL-6 overproduction in the TME is associated with a functional defect in DCs in cancer patients." (PMID 35267487, 2022). "Our results underline that IL-6 and TNFα SNPs could be potential markers of baseline pain intensity and opioid dose requirements in pediatric cancer patients." (PMID 35335997, 2022). "CRP can induce a variety of inflammatory cytokines associated with cancers, such as interleukin-6." (PMID 35300627, 2022). "Through in-depth analyses, we observed that the TRP score was positively associated with many malignant pathways in pan-cancer, such as IL6–JAK–STAT3 signalling, interferon-gamma response, and inflammatory response—all of which were closely associated with TIME." (PMID 35493463, 2022). "Besides, IL-6 has been reported to be overexpressed in patients with cancers, including OSCC, which is associated with poor prognosis." (PMID 35513871, 2022). "Several cancer-related pathways may be more active in high-risk LGGs, such as IL6 JAK STAT3 signaling pathway." (PMID 36193491, 2022). "The IL‐6 levels have been associated with weight loss in certain human cancers." (PMID 36458537, 2022). "We hypothesized that RT may protect against the excessive activation of STAT3 by the overabundance of IL-6 and oxidative stress during cancer-induced muscle atrophy and strength loss." (PMID 35847939, 2022). "Inflammatory cytokines produced by cancer cells, such as interleukin (IL)‐1, IL‐6, and tumor necrosis factor‐α, induce skeletal muscle loss, lipolysis, and anorexia, suggesting cancer‐associated inflammation is the main pathogenesis of cancer cachexia." (PMID 36394148, 2022). "The Anti-IL-6 m Ab therapy, which reduced the incidence of anorexia and cachexia associated with cancer, may also be effective in the treatment of cancer patients." (PMID 36140470, 2022). "Furthermore, the cancer-causing mechanism was linked to the MyD88-dependent stimulation of IL-6 production by Kupfer cells (macrophages) in the chemically damaged liver by observing that the sex bias in HCC development was abrogated in MyD88−/− mice." (PMID 35406728, 2022).
cancer (continued). "Additionally, β3AR activation was linked to WAT browning while neutralization of IL-6 or inhibition of β3AR significantly ameliorated cancer cachexia." (PMID 35646636, 2022). "Moreover, IL-6/IL-11 activates STAT3 in cancer-associated fibroblasts (CAFs) to promote CRC progression and poor prognosis." (PMID 35783510, 2022). "It is possible that a person with ASCs that produce high amounts of IL-6 may be at a greater risk for cancer due to a shift in immune cells toward macrophages rather than dendritic cells." (PMID 36293398, 2022). "IL-6 and IL-1β, two of the cardinal senescent cytokines, play central roles in tumor initiation and growth, partially explaining the aging-associated susceptibility to cancers." (PMID 35821823, 2022). "In addition to regulating angiogenesis and morphogenesis, mesenchymal stromal cells (MSCs) have been demonstrated to recruit cancer-associated fibroblasts (CAFs), IL-6 and M2macrophage, all of which have been linked to cancer progression." (PMID 36439472, 2022). "Moreover, in other cancers, elevated IL-6 levels have been linked to treatment resistance and reduced survival." (PMID 35740687, 2022). "Therefore, our study only suggests, in the absence of an autophagic flux experiment, that the phosphorylation of STAT3 in response to exacerbated IL-6 and ROS formation seems to be associated with autophagy activation during cancer cachexia." (PMID 35847939, 2022). "Because neoplastic elements in human tumors were immunoreactive to IL-6 antibodies and several cancer cell lines constitutively secreted IL-6, we investigated whether cancer-associated genetic changes might upregulate IL-6 gene expression." (PMID 35406728, 2022). "Several cancer-related pathways may be more active in high-risk LGGs, such as IL6 JAK STAT3 signaling pathway and ECM receptor interaction." (PMID 36193491, 2022). "Inflammation is one of the hallmarks of cancer and it was found that CC variant of rs2853669 was linked to increased level of inflammatory cytokines IL-6 and TNF-α, which may contribute to cancer malignancy." (PMID 34440361, 2021). "In addition, IL6 levels are also associated with an increased risk of developing different types of cancer." (PMID 34447383, 2021). "However, the critical role of IL-6 in tumorigenesis is even more underlined by the correlation of high levels of circulating IL-6 with a poor prognosis and lower survival of cancer patients." (PMID 34671021, 2021). "They reported that the IL-6 gene is significantly associated with the overall cancer risk." (PMID 33684135, 2021). "IL6 is a key pro-inflammatory cytokine that drives chronic inflammation in a number of ways and has been linked to poor survival outcomes in various forms of cancer." (PMID 34901003, 2021). "In addition, over-expression of IL-6 aggravates weight loss of cancer cachexia in ApcMin/+ mice, whereas increased knockout of IL-6 reverses that." (PMID 34863141, 2021). "In contrast to insulin resistance, cancer cachexia may be driven by inflammation as and IL-6, IL-1, and TNF-α per se can cause muscle catabolism." (PMID 33801684, 2021). "The pro-inflammatory factors of IL-1 and IL-6 from TAMs facilitate the invasion of cancer cells, and this process might be associated with their receptor up-regulation." (PMID 34379689, 2021). "A number of adverse cancer-associated effects are related to IL-6 signaling." (PMID 34681685, 2021). "In a variety of cancers, IL-6 is overexpressed and is associated with the activity of STAT3." (PMID 34445405, 2021). "Indeed, soy isoflavone was found to increase serum IL-6 in postmenopausal women and thus enhancing the immune surveillance associated with lower incidence of cancer in parts of the world characterized by higher soy intake." (PMID 34950252, 2021). "Study also reveals that IL-6 might induce fat loss in cancer cachexia by regulating white adipose tissue lipolysis and browning." (PMID 34888248, 2021).
cancer (continued). "IL-6 was first recognized as a B-cell stimulating factor but we now know that the cytokine plays a pivotal role in the orchestration of inflammatory processes as well as in inflammation associated cancer." (PMID 34141712, 2021). "When GC MSCs secrete IL-6 to activate neutrophils and inhibit their apoptosis, the GC-associated neutrophils in turn induce differentiation of GC MSCs into cancer-associated fibroblasts (CAFs) which may produce even more IL-6." (PMID 34944729, 2021). "Interestingly, in many cases, cancer patients with high plasma levels of TPO also had increased production of interleukin (IL)-6, and both parameters were linked to advanced disease and poor survival." (PMID 34322381, 2021). "In advanced stage cancers, IL-6 is highly associated with disease progression." (PMID 34531850, 2021). "IL-6 activates embryonic stemness during the initiation of PGCCs and can reprogram normal fibroblasts into cancer-associated fibroblasts (CAFs) via increased collagen synthesis, activation of VEGF expression, and enrichment of CAFs and the GPR77 + /CD10 + fibroblast subpopulation." (PMID 34588424, 2021). "Interleukin 6 (IL6) is a cytokine associated with poor prognosis of many cancers." (PMID 34868901, 2021). "Notably, IL-6 levels are also diagnostic markers of therapeutic response and prognostic indicators of survival probability in certain types of cancer." (PMID 34001144, 2021). "Indeed, leptin is closely associated with cytokine levels, mainly IL-6, and has been identified as a mediator of the metabolic and immunological changes observed in advanced cancer patients." (PMID 33809200, 2021). "IL-6 can be generated in a local cytokine niche and is produced by diverse tissues, notably proinflammatory cell types, containing dendritic cells (DCs), Mφ, MDSCs, T lymphocytes, cancer-associated fibroblasts, and endothelial cells." (PMID 33981768, 2021). "Recently, the cytokines IL-6, IL-4 and alternatively activated macrophages that secrete norepinephrine have been implicated in mediating beige adipocyte formation during burn trauma, cancer, calorie restriction, and cold-induced WAT browning." (PMID 34423787, 2021). "The elevation of IL-6 has been linked to the “browning” phenomenon and could be one of the reasons for cancer cachexia development." (PMID 34440886, 2021). "Then, IL-6 and leptin could represent early markers of the main symptoms and metabolic alterations associated with the pathogenesis of cancer cachexia." (PMID 33809200, 2021). "The pleiotropic interleukin-6 (IL6) is a cytokine that has been implicated in many cancers." (PMID 34945807, 2021). "Even though several studies positively correlated elevated serum IL-6 levels with a poor prognosis, further studies are required to clearly determine whether IL-6 is a cause or consequence in different types of cancer." (PMID 34445170, 2021). "Cancer-induced IL-6, leukemia inhibitory factor, etc. are also associated with adipose wasting." (PMID 34445197, 2021). "The subgroup analysis based on ethnicity, the Asian population suggested that the IL-6 -572G/C polymorphism was significantly associated with increasing overall cancer risk for the over-dominant model [CG vs. CC + GG: OR = 1.13, 95% CI = 1.01–1.27, p-value = 0.0293]." (PMID 33684135, 2021). "Moreover, numerous studies have revealed associations of high levels of inflammatory markers, such as C-reactive protein (CRP) and IL6, with an increased risk of developing different types of cancer." (PMID 34685542, 2021). "Several studies have suggested that NLR levels indicate cancer-associated inflammatory response, lymphocyte-mediated antitumor response, and production of cytokines, including tumor necrosis factor, interleukin-1, interleukin-6, and angiogenic factor VEGF." (PMID 34461485, 2021).